BRCA1 (BRCA1 DNA repair associated)
Diseases named in the same sentence as BRCA1 in open-access papers (continued):
Sharing a sentence is not in itself a finding about the gene and the disease.
tumor (continued). "•Preclinical study: PARPi’s plus AZA/DAC increased PARPi efficacy and resulted in additional tumor inhibition in TNBC cells harboring wild-type BRCA1 compared with each drug alone." (PMID 34778045, 2021). "The overall RTV for AZD2281-treated mice bearing Brca1-mutant tumor allografts was 59.5% compared with vehicle-treated controls." (PMID 33767581, 2021). "The RNAseq data showed that the median frequency of DMD alterations in non-myogenic tumours (3.4%) was higher than that in other common tumour suppressor genes, such as BRCA1 (1.6%), BRCA2 (2.8%) and PTEN (3%)." (PMID 33188621, 2021). "A total of 39 307 tumor samples from 37 259 patients were included in the study, including 1977 patients (5.3%) with a BRCA1/2 alteration." (PMID 33961040, 2021). "Utilizing GEM ExTra® Tumor and normal WES sequencing the aligned reads were examined to see if the BRCA1 mutation was lost via clonal evolution." (PMID 34504655, 2021). "A total of 10 patients with a familiar predisposition for EOC and a known mutation in BRCA1, BRCA2 or RAD51C and available tumor tissue were included in the cohort." (PMID 33482905, 2021). "BRCA1 can modulate tumor growth through its transcriptional regulation of angiogenic factors and the stability of HIF1α." (PMID 35008272, 2021). "In recent decade, many tumor-suppressor genes such as BRCA1, BRCA2 and BLM and downstream nucleases including XPF and MRE11 have been suggested as proteins that are important for R-loop tolerance and removal." (PMID 33857133, 2021). "Gene expression of FOXM1 and its targets BRCA1/2 and RAD51 were investigated together with tumor susceptibility." (PMID 33668819, 2021). "We also noted p18−/−;Brca1+/− tumor cells that had invaded into muscles were marked by high levels of Pdgfrβ expression." (PMID 33478572, 2021). "This isoform heterodimerises with BRCA1, and it is required for BRCA1 relocation and its known tumour-suppressive function as a guardian of genetic stability." (PMID 34884690, 2021). "In particular, given that pharmaceutical inhibition of PDGFRβ efficiently promotes cell death of BRCA1-deficient tumor cells, it indicates the potential to tailor specific therapies to BLBC patients with BRCA1 deficiency." (PMID 33478572, 2021). "Consistent with BRCA1 neoplasms involving the breast and ovaries, the BRCA1 status of the patient's primary tumor likely increased the risk of central nervous system dissemination." (PMID 33681280, 2021). "Another example concerns the tumor suppressor and master of nuclear integrity BRCA1 (BReast CAncer 1), which harbors, at aminoacid residues 1664–1696 within the first BRCT repeat, a lipid-binding motif." (PMID 34884734, 2021). "While BRCA1 and BRCA2 deficient tumours are associated with increased immune infiltrates, rates of response to ICI are low." (PMID 35096825, 2021). "Nevertheless, in patients with breast tumors, low expression of XRCC1, ATM, and BRCA1 correlates with high proliferation indexes, higher tumor grade, and the presence of dedifferentiated cells." (PMID 34930377, 2021). "Further investigation of these results is needed in order to potentially personalize treatment based on race and tumor BRCA1 expression levels." (PMID 34611475, 2021). "A progressive enhancement in tumor growth was detected with both iMSCs, but with a higher rate for BRCA1+/− iMSCs compared to WT." (PMID 33513753, 2021). "Curcumin, which exists in the rhizomes of Curcuma longa, has been approved for the treatment of CRC, and it can inhibit tumor occurrence by inducing the expression of a suppressor lncRNA neighbor of BRCA1 gene 2 (NBR2)." (PMID 34778084, 2021).
tumor (continued). "The critical roles of BRCA1/2 in DNA replication also explain why BRCA-deficient cells and tumours are particularly vulnerable to DNA damage induced by chemotherapy." (PMID 34389725, 2021). "We found that age, sex, tumor stage, metastasis score, and tumor size were relatively evenly distributed across BRCA1 mRNA-low versus -high groups." (PMID 34611475, 2021). "As an important tumor suppressor gene, BRCA1 gene is involved in the upregulation of gene expression of protective antioxidant response and antioxidant response transcription factors." (PMID 34659642, 2021). "Among the germline mutations, BRCA1 and BRCA2 tumor suppression genes are inherited in an autosomal dominant manner with incomplete penetrance." (PMID 34884434, 2021). "As cells deficient in BRCA1/2 cannot repair DSBs, they are particularly sensitive to the effects of PARP inhibition, resulting in synthetic lethality in tumor cells carrying the mutation while normal cells are spared." (PMID 34504648, 2021). "As expected, restored BRCA1 expression has been correlated with the re-gained ability of the tumour to form RAD51 foci." (PMID 35008208, 2021). "Epigenetics was argued over the years to supplement tumor evolution with an alternative mechanism for silencing tumor suppressors (e.g., BRCA1), but its overall impact on tumors has remained controversial." (PMID 34518533, 2021). "In addition, BRCA1 somatic variants may be detected in 8–10% of the tumor samples." (PMID 34944094, 2021). "To investigate these patient populations further, we evaluated distribution of age, sex, tumor stage, metastasis score, tumor size, lymph node stage, and race across BRCA1 mRNA-low versus -high CRC." (PMID 34611475, 2021). "BRCA1 is a tumour suppressor gene coding for a large protein containing multiple functional domains, which interacts with multiple other proteins." (PMID 34855882, 2021). "Accordingly, based on complementary mechanisms of action, the effects of combining ABBV-176 with the PARP inhibitor ABT-888 (Veliparib) were investigated in the CTG-0670 TNB BRCA1 deficient, BRCA2 mutant PDX tumor models." (PMID 34107902, 2021). "The cutoffs of ATM (0.3) and BRCA1 (1.0) expressions (tumor/non-tumor) were determined by receiver operating characteristic analysis." (PMID 34068585, 2021). "For example: MDA-MB-231 and MDA-MB468 have wild type of BRCA1, whereas HCC1937 has mutated BRCA1, Thus, the protein levels of DYRK1B in tumor tissues and the regulation mechanisms of DYRK1B in tumors need further empirical verification." (PMID 34830933, 2021). "The observation that SHLD2 or MAD2L2 siRNAs caused sensitivity to ART558 in a BRCA1 mutant cell line raised the possibility that a Polθ inhibitor could be used to target PARP inhibitor resistance caused by Shieldin complex defects when these occur in BRCA1 mutant tumour cells." (PMID 34140467, 2021). "BRCA1 plays a key role in the maintenance of genomic integrity, which is an essential component of its tumor-suppressing function." (PMID 33922503, 2021). "BRCA2-associated tumors demonstrate higher sensitivity to trabectedin or lurbinectedin than BRCA1-driven neoplasms." (PMID 34454564, 2021). "In our paired cohort of 200 patients, we demonstrated a 100% detection of 37 germline BRCA1/2 variants (PV and VUS) with tumor testing, including one large copy number variant." (PMID 33030818, 2021).
tumor (continued). "The pathogenic germline variants in mCRPC, recurrent germline and somatic variants, and hotspot positions in different tumour types were mapped onto ATM, BRCA1, BRCA2, and MUTYH available structures, in order to find 3D-clusters of variants." (PMID 34253785, 2021). "Twenty-two FA-related genes have been identified including tumor suppressors BRCA1 (FANCS) and BRCA2 (FANCD1)." (PMID 34504103, 2021). "We also found that a patient-derived tumour ex vivo culture with low BRCA1 and 53BP1 expression was resistant to olaparib or carboplatin but sensitive to ART558." (PMID 34140467, 2021). "Here, we present a highly sensitive and specific liquid biopsy assay that assesses BRCA1 gene promoter hypermethylation on circulating tumor DNA (ctDNA) isolated from blood plasma." (PMID 34601813, 2021). "In line with this, pathogenic BRCA1, BRCA2 and PALB2 mutations contribute to distinct tumor inflammatory architecture." (PMID 34572943, 2021). "BARD1 and BRIP1 are both tumor suppressors, that act in the repair of double-stranded DNA damage, with proteins, interact with BRCA1." (PMID 34768979, 2021). "In summary, PALB2 tumours show the homologous recombination deficiencies characteristic of BRCA1 and BRCA2 tumours, and highlight the potential clinical relevance of PALB2 mutational status in guiding therapeutic choices." (PMID 33893315, 2021). "Of 64 patients with data from tumor tissue samples, 10 (15.6%) had a deleterious alteration in a DNA damage repair pathway gene, including four with a deleterious BRCA1 or BRCA2 alteration." (PMID 34030643, 2021). "All 37 germline BRCA1/2 variants (PV and VUS) were identified on tumor testing, demonstrating 100% detection of germline variants through FFPE tumor testing." (PMID 33030818, 2021). "While age, sex, tumor and metastasis score, and tumor size were relatively evenly distributed across BRCA1 mRNA-low versus -high groups, subtypes were unevenly distributed in a way that made it difficult to make any conclusions." (PMID 34611475, 2021). "Treatment of Brca1-mutant tumor-engrafted mice with X-rays reduced tumor progression by 27.9% compared with untreated controls." (PMID 33767581, 2021). "Since targeting R-loops has been considered as a tumor therapy approach, an excess of TERRA R-loops in BRCA1-deficient cells represents a potential target for R-loop-directed therapy for BRCA1 mutation carriers." (PMID 34112789, 2021). "These contradictory observations warrant that more studies are needed to clarify the role of the E3 ubiquitin ligase activity of BRCA1 in tumour suppression and therapy response." (PMID 33755171, 2021). "This ligase activity is paramount in maintaining genomic integrity via the tumour suppressive function of BRCA1." (PMID 34771713, 2021). "Dosing of rats bearing established MDA-MB-436 BRCA1/SHLD2 defective tumours with ART812 resulted in significant tumour inhibition and was well-tolerated." (PMID 34140467, 2021). "As expected, overall survival (p = 0.0088) and disease-free survival (p = 0.0575) were higher in the patients bearing a tumor with shallow deletion of both BECN1 and BRCA1 compared to those bearing a tumor with a diploid CNV of the two tumor suppressor genes." (PMID 33670664, 2021). "In HeLa cells, the tumor suppressor BRCA1 directly binds to IP3R and increases the probability of IP3R opening, which is dedicated to stimulating Ca2+-dependent apoptosis." (PMID 34512174, 2021). "To investigate BRCA1 mRNA-low versus -high BC patient populations further, we evaluated distribution of age, sex, tumor stage, metastasis score, tumor size, subtype, and race." (PMID 34611475, 2021). "Another example of a nuclear factor with a dual role in the nucleus and the cytoplasm is the already mentioned tumor suppressor BRCA1." (PMID 34884734, 2021).
tumor (continued). "The BRCA1&2 (BReast-CAncer-1 and 2) proteins are involved in cell cycle control and as tumor suppressors act in DNA repair." (PMID 33513663, 2021). "While it is well established that the tumor suppressors BRCA1 and BRCA2 function in DNA repair and homologous recombination in somatic cells, the functions of BRCA1 and BRCA2 in meiosis have received less attention." (PMID 33996823, 2021). "Taken together, our results, support the existing body of literature characterizing BRCA1 and BRCA2 mutations as predictive of chemo‐response and potentially associated with high tumor immune cell infiltration and PD‐L1 IHC expression." (PMID 33811746, 2021). "The results demonstrated that tumor formation capacity of both B477 and G600 cells is obviously inhibited in the knockout groups compared with the control cells, especially in the Brca1 mutant G600 cells." (PMID 34815798, 2021). "In older patients, only 4.6% of patients ≥60 years had a BRCA1-null tumor, while 16.2% showed BRCA1 promoter hypermethylation." (PMID 33568222, 2021). "Genomic characteristics, such as the oncogene activation (e.g., ERBB2 amplification, EGFR tyrosine kinase mutation) and inactivation of tumor suppressor genes (e.g., MMR, BRCA1/2) have shown a strong correlation with clinical response to target therapy." (PMID 34047476, 2021). "In August 2018, the province of Ontario implemented clinical reflex tumor BRCA1/2 testing as a funded, standard‐of‐care service for all cases of newly diagnosed HGSC and previously diagnosed cases with negative germline BRCA1/2 testing." (PMID 33030818, 2021). "Previous data showed that shallow CNV of BECN1 and BRCA1 correlates with low level of mRNA in the tumor and with better prognosis of the patients." (PMID 33670664, 2021). "A preclinical study showed that PARPi’s plus DNMT inhibitors (DNMTi’s, 5-azacytidine/AZA, decitabine/DAC) increased PARPi efficacy and resulted in additional tumor inhibition in TNBC cells harboring wild-type BRCA1 compared with each drug alone." (PMID 34778045, 2021). "When the number and intensity of positive cells were quantified, we found that the H scores for Vim in p18mt;Gata3+/-tumor cells were comparable with the H scores in p18mt;Brca1+/- counterparts." (PMID 34373738, 2021). "As previously reported, BRCA1 mRNA-low tumor expression positively correlated with BC patient survival but was negatively associated in CRC." (PMID 34611475, 2021). "Deleterious alterations in DDR genes associated with increased sensitivity to PARP inhibitors in other tumor types (e.g. BRCA1, BRCA2, PALB2, RAD51C and RAD51D) were infrequent (9.4%) in ATLAS." (PMID 34030643, 2021). "To understand why co-ablation of Brca1 with Palb2 led to delayed tumor formation, we analyzed markers of DNA damage, oxidative stress, and apoptosis in Brca1 and Palb2 single and double deletion mammary glands." (PMID 33893322, 2021). "Our results indicate BRCA1 mRNA-low CRC tended to be more advanced in tumor, metastasis, and lymph node stages, possibly explaining the worse overall survival seen in this group." (PMID 34611475, 2021). "Our previous work has identified the tumor suppressors BRCA1 and CHK2 and the oncogenic kinase AURKA as regulators of mitotic microtubule growth rates and for W-CIN." (PMID 33168930, 2021). "Samples from each tumor were stained for BRCA1 and reviewed independently by gynecologic pathologists blinded to the BRCA status." (PMID 34820332, 2021). "Skin samples were obtained from pathogenic BRCA1 variant carriers and VUS BRCA1 carriers undergoing either risk-reducing mastectomy (K381X, A1708E) or tumour-removal surgery (C61G, G462R, Y856H, D1733G, Q1811K, V1687G)." (PMID 34855882, 2021).
tumor (continued). "Tumor analysis highlighted germline variation in HR-related repair genes, particularly BRCA1, PALB2 and RAD51C, to have a potential driver role in EC development based on the presence of mutational signature indicative of HR deficiency." (PMID 33917078, 2021). "RRM2 expression induced by BRCA1, traditionally regarded as tumor suppressor, promotes tumorigenicity in GBM cells." (PMID 34568059, 2021). "FOXM1 inhibition was therefore shown to counteract this tumor adaption of increased HR and to downregulate BRCA1/2 and RAD51." (PMID 33668819, 2021). "NBR2 was initially identified as a tumor suppressor similar to BRCA1, and plenty of evidence has verified this perspective." (PMID 34926299, 2021). "The universal tumor BRCA1/2 testing workflow has been shown to be a feasible, effective and robust option in daily pathology practice, and well perceived by gynecologists and patients." (PMID 33233347, 2020). "BPA increases the methylation levels of key genes associated with tumor development (e.g., BRCA1, CDKN2A, etc.), altering the epigenome in order to promote proliferation, senescence, and tumor development." (PMID 32197344, 2020). "The conditional Δ11 allele, Brca1flox11, has been used in many studies to examine tissue-specific function of BRCA1 and to establish tissue-specific tumor models." (PMID 32257107, 2020). "We demonstrate that BRCA1 hypermethylation is twice as frequent as BRCA1-null tumors in early-stage unselected TNBC and that elevated BRCA1 promoter methylation is detectable in peripheral blood DNA of patients with hypermethylation in the tumor." (PMID 32719340, 2020). "The differentially classified samples included four non-BRCA1/2 tumours (FBC050798, FBC020636, FBC060411 and FBC070086) and one tumour from pathogenic BRCA2 mutation carrier (FBC013587)." (PMID 32818150, 2020). "In the case of PyMT tumor cells, higher levels of Ltf, Spp1, Anxa1 and Cldn4 distinguish them from Neu and BRCA1-null tumor cells, and some of these genes have been associated with luminal progenitors." (PMID 32840210, 2020). "BRCA1 is a tumor suppressor with known functions in DNA repair, transcription regulation, cell cycle control, and apoptosis." (PMID 32290274, 2020). "A total of 277 genes were differentially expressed between BRCA1 and BRCAx tumours, and 31 genes were differentially expressed between BRCA2 pathogenic variants and BRCAx tumours." (PMID 33081408, 2020). "A statistically significant correlation was found between BRCA1 expression with the stage and grade of the tumor (p-value<0.05)." (PMID 32334465, 2020). "In the predicted truncated BRCA1 protein, p.Gly1803GlnfsTer11, the last 61 amino acids are lost, including part of the BRCA1 carboxyl terminal (BRCT) domain that is essential for the tumour-suppressor function of BRCA1." (PMID 32203205, 2020). "A critical comprehensive appraisal of these additional factors influencing BRCA1 expression is necessary, in order to better define the tumor population sensitive to CT." (PMID 32235500, 2020). "This showed that patients with BRCA1/2 mutant tumours benefited most from maintenance treatment with 21.0 versus 5.5 months (HR 0.27 [95% CI 0.17–0.41])." (PMID 32833070, 2020). "BRCA1 is a well-known tumor suppressor, but also has oncogenic roles with RAD51 through its DNA-repair function." (PMID 32572160, 2020). "The “FoundationFocusTM CDx BRCA LOH” detects mutations in the BRCA1/2 and the percentage of the genome affected by LOH in DNA from tumor tissue samples." (PMID 32455595, 2020).